INS (insulin)
Diseases named in the same sentence as INS in open-access papers (continued):
Sharing a sentence is not in itself a finding about the gene and the disease.
type 2 diabetes (continued). "Type 2 diabetes was reported for 70% of patients; mean disease duration in the study group was 12.14 years (SD = 9.54); 26% of patients received antidiabetic medications; 24% of patients received both medications and insulin." (PMID 32689971, 2020). "This suggests that a dietetic integration with Chlorella sorokiniana can be useful in the prevention of the disfunction in which mitochondrial oxidative damage and ROS production play a putative role, such as the insulin resistance that preludes the onset of type 2 diabetes." (PMID 32957734, 2020). "Long-term trials are needed to ascertain whether JD as a standalone intervention can prevent type 2 diabetes in healthy subjects and reduce insulin and diabetic medications in type 2 diabetic patients." (PMID 32215273, 2020). "Other studies have found a decrease in the number of Bifidobacteria in the gut of patients with type 2 diabetes, and they believe that impaired glucose tolerance and insufficient insulin secretion in patients with type 2 diabetes are related to a decrease in the number of Bifidobacterium." (PMID 33062017, 2020). "Moreover, globular adiponectin supplementation increased insulin secretion and decreased glucose levels in rats with Type 2 diabetes and NAFLD." (PMID 32492866, 2020). "Type 2 diabetes mellitus (T2DM) is a chronic metabolic disease that requires continuous medical care in which the body can not benefit sufficiently from carbohydrates, fats and proteins due to insulin deficiency or impairment of insulin action." (PMID 32267361, 2020). "On the other hand, insulin was not able to improve type 2 diabetes prediction when it was added to the FOS risk score." (PMID 32957570, 2020). "Furthermore, adropin is able to improve insulin sensitivity and reduce hyperglycemia in animal models of type 2 diabetes." (PMID 32012786, 2020). "For instance, microRNA 144 could repress insulin signaling during type 2 diabetes mellitus development through suppressing the expression of Insulin Receptor Substrate 1 (IRS1)." (PMID 32258168, 2020). "Excess GC may play an important role in the pathogenesis of obesity and type 2 diabetes by directly antagonizing insulin action and inhibiting insulin release." (PMID 32792855, 2020). "In summary, CCR5 may be involved in the pathogenesis of type 2 diabetes through mediating insulin resistance and hypothalamic insulin signaling regulation." (PMID 32194402, 2020). "The basic model of insulin use in type 2 diabetes (users n=919, non-users=2413) showed associations with several derived glycans, none of which remained significant in the full model." (PMID 32616483, 2020). "Functional enrichment analysis showed significant enrichment of biological processes that can disrupt the normal glucose, insulin, and glucagon homeostasis in the cell by positively and negatively regulating them leading to the development of type II diabetes mellitus." (PMID 32993798, 2020). "The patients with Type 2 diabetes were both on insulin therapy preceding the study." (PMID 33519707, 2020). "In Zucker's fa/fa obese rat model, SIRT1 activating factor (SRT1720) could improve type 2 diabetes by increasing systemic insulin sensitivity and mitochondrial capacity, as well as reducing hepatic glucose production." (PMID 32280711, 2020). "In agreement with this hypothesis, data from the literature indicate a decrease of IRAP translocation in response to insulin in adipocytes and skeletal muscle in diabetic rats and in patients with type 2 diabetes." (PMID 33665204, 2020). "The activation of insulin and Wnt signaling pathways may finally worsen liver steatosis in a feed-forward loop in the pathological context of obesity and type 2 diabetes." (PMID 32198362, 2020).
type 2 diabetes (continued). "Patients with type 2 diabetes carrying B1B1 genotype had a significantly lower insulin (B1B1: -15.07 ± 3.77 mIU/mL vs. B1B2: -4.75 ± 2.20 mIU/mL and B2B2: 0.76 ± 3.77 mIU/mL) and HOMA-IR (B1B1: -1.74 ± 0.45 vs. B2B2: 0.10 ± 0.45) than carriers of the B2 allele in the sesame oil period." (PMID 33123324, 2020). "The proportion of patients receiving insulin increased over the years, probably due to the slight increase in the prevalence of type 1 diabetes and the increasing replacement of secretagogues with insulin in type 2 diabetes." (PMID 32704570, 2020). "Therefore, a less invasive and passive alternative to insulin therapy is required for people with type-II diabetes." (PMID 32785196, 2020). "Furthermore, the PD has been shown to improve insulin sensitivity and reduce hepatic lipid levels among patients with type 2 diabetes." (PMID 32069218, 2020). "In vivo, 4 weeks’ administration of 70 % ethanol FD extract (125, 250 and 500 mg/kg/d) to streptozotocin–nicotinamide-induced type 2 diabetic rats reversed the abnormal changes of blood glucose, insulin, total Hb, GLUT2, lipid profile, and oxidative stress in liver and pancreas." (PMID 32042410, 2020). "On one hand, continuous positive airway pressure (CPAP) over 6 months was shown to improve glycaemic control and insulin resistance in people with type 2 diabetes and obstructive sleep apnoea but on the other, one earlier trial of CPAP over 3 months found no such benefits." (PMID 32671413, 2020). "Such factors might include the presence of type 2 diabetes, which is common in obesity, leads to reduced secretion of insulin and hyperglycaemia, and may influence plasticity." (PMID 32839377, 2020). "Furthermore, specific comparison of metoprolol and carvedilol in patients with type 2 diabetes showed a detrimental effect of metoprolol on insulin‐stimulated endothelial function." (PMID 32170823, 2020). "Patients with type 2 diabetes using both insulin treatment and oral glucose-lowering medication may have poorer glucose metabolism and glycaemic control and poorer sleep quality than those not using these medications." (PMID 32671413, 2020). "GLP1RA may be a relatively safe and effective treatment for kidney transplant recipients with type 2 diabetes that allows for a reduction in insulin requirements." (PMID 32095510, 2020). "A key feature of type 2 diabetes is a resistance to insulin." (PMID 32432228, 2020). "Our analysis identifies several well-known disease-related genes that are not identified by GWAS, including BRCA1 in Breast Cancer, Amyloid Precursor Protein (APP) in Alzheimer’s Disease, INS in A1C measurement and Type 2 Diabetes, and PCSK9 in LDL cholesterol, amongst others." (PMID 32678846, 2020). "Although the role of SMBG is controversial in patients with type 2 diabetes treated with oral agents, SMBG in patients with type 2 diabetes treated with insulin is very important; it is useful for adjusting insulin dosage, guiding nutrition therapy and physical activity, and preventing hypoglycemia." (PMID 32141838, 2020). "ATF2 targets genes are involved in insulin action, β cell function, and type II diabetes mellitus." (PMID 32993798, 2020). "Therefore, Vitamin D and omega-3 co-supplementation can be considered for preventing diabetes type 2 because of their positive effects on fasting blood glucose and insulin." (PMID 32435279, 2020). "From September 1, 2018, to May 31, 2019, a total of 5011 patients with type 2 diabetes who were older than 18 years and were receiving insulin therapy were enrolled in the study." (PMID 32141838, 2020). "The change of insulin sensibility is an important pathogenesis of type 2 diabetes." (PMID 32818031, 2020). "The association between anthropometric measurements, insulin sensitivity and liver fat with tissue-specific GC metabolism has not been tested among patients with type 2 diabetes." (PMID 32069218, 2020).
type 2 diabetes (continued). "In the future, it will be interesting to learn whether SPARC can improve insulin secretion in patients with type 2 diabetes through RGS4 pathway." (PMID 33067534, 2020). "In summary, vagus nerve stimulation modulates glycemia by effecting glucagon and insulin secretions, and high‐frequency 40 kHz stimulation may have potential application for the treatment of type 2 diabetes." (PMID 32512650, 2020). "Thus, there is a desire to develop new forms of delivery devices to administer insulin to treat type-II diabetes." (PMID 32785196, 2020). "In addition to the beneficial metabolic effects in diet-induced obesity, adropin reduces blood glucose level, improves insulin sensitivity, and suppresses inflammatory markers in a rat model of type 2 diabetes." (PMID 32012786, 2020). "The possibility to induce classically conditioned insulin release as demonstrated by Stockhorst, de Fries, might for example be applied for improving therapies for patients with diabetes type-2 who suffer from dysfunctional insulin release." (PMID 32191722, 2020). "Thus, the decline of SCFAs or, in particular, butyrate producer bacteria in type 2 diabetes individuals is directly affecting insulin signaling and sugar homeostasis." (PMID 33062716, 2020). "A genetic polymorphism in MTRR in adipose tissue may prompt endoplasmic reticular stress, leading to inhibited insulin signaling, and thus resulting in IR and type 2 diabetes." (PMID 32850306, 2020). "For example, neither rs738409 C>G in PNPLA3 nor rs58542926 C>T near TM6SF2 (risk alleles for type 2 diabetes) were significantly associated with differences in fasting insulin, glucose or HbA1c." (PMID 32720691, 2020). "Previously, we have demonstrated that acute C peptide response (ACPR) evaluated by the arginine stimulation test may be superior to other commonly used β-cell function parameters to reflect glycemic fluctuation in insulin-treated patients with type 2 diabetes." (PMID 32775460, 2020). "It was also found that milk protein intake could improve hyperglycemia by stimulating insulin secretion in individuals with metabolic syndrome or type 2 diabetes mellitus (T2DM)." (PMID 32724618, 2020). "Induction of Hsp70 may have a favorable impact on the microvascular complications of type 2 diabetes, and improve the insulin sensitivity of type 2 diabetics." (PMID 33365011, 2020). "Our results indicate that consumption of a dessert with a low glycemic index/glycemic load ameliorates glucose and insulin responses in patients with type 2 diabetes compared to a conventional dessert with similar content of available carbohydrates but different sugar and fiber content." (PMID 32698325, 2020). "A decrease in insulin sensitivity is the initial pathology of type 2 diabetes." (PMID 32818031, 2020). "Despite participants having type 2 diabetes for on average of 13 years, the average insulin usage in the intervention group fell to 27 units/day, with 39.4% of participants stopping insulin completely, compared with the control group who took 52 units/day, with only 5.6% stopping insulin." (PMID 32049634, 2020). "Interestingly, Dorea and Dialister were found to be related with insulin secretion and fasting blood glucose, suggesting their role in type 2 diabetes development in overweight-obese individuals." (PMID 32708278, 2020). "Our aim was to determine if BMAT is an insulin-sensitive tissue, and whether the insulin sensitivity is altered in obesity or type 2 diabetes (T2DM)." (PMID 32311037, 2020). "Therefore, herbal sweeteners such as stevia (Stevia rebaudiana) are receiving much attention as natural alternatives to artificial sweeteners and sugars, especially in management of insulin sensitivity and type 2 diabetes (Reid, 2016 ▶; Romo-Romo, 2016 ▶)." (PMID 32257884, 2020).
type 2 diabetes (continued). "According to authors, these findings may suggest that this subset of TAARs may be regulators of insulin secretion in pancreatic β -cells, as such they may be potential targets for treatment of type 2 diabetes." (PMID 33488196, 2020). "In addition, PGC-1α has also been induced in the liver of a type 1 diabetes experimental model and in ob/ob mice, a type 2 diabetes model with high insulin levels, but intense insulin resistance." (PMID 32215168, 2020). "Our findings indicate that PA may reduce the incidence of LADA through the same mechanism linking PA to type 2 diabetes, namely through beneficial effects on body weight and improved insulin sensitivity." (PMID 32835373, 2020). "The evidence suggests that this is not the best process to achieve the optimal glycemic control, and self-titration of insulin in type 2 diabetes may be more effective." (PMID 32406854, 2020). "Indeed, physical activity by patients with type 2 diabetes markedly improves the impaired insulin action and is considered a cornerstone in the treatment along with diet and medication." (PMID 33519500, 2020). "Additionally it has been described for β-cells themselves to over-produce NO in diabetes type II, while the low production of NO results in insulin excretion." (PMID 32604946, 2020). "Systemically, metformin therapy lowers blood glucose in type 2 diabetes patients by targeting hepatic gluconeogenesis and by increasing glucose uptake in the peripheral tissues, mainly muscles, and indirectly reduces the insulin blood levels by counteracting insulin resistance." (PMID 33182253, 2020). "We then assessed whether the level of ci-Ins2 and its parent gene Ins2 are modified in the islets of type 2 diabetes models exhibiting impaired insulin secretion." (PMID 33154349, 2020). "First, pregnant women with type 2 diabetes treated with insulin may have poor glycemic control and a higher rate of comorbidities at the time of conception, which may lead to adverse pregnancy outcomes." (PMID 32887578, 2020). "Moreover, early age at PHV predicted insulin treatment of type 2 diabetes (OR 1.25 per year decrease in age at PHV, 95% CI 1.17, 1.33)." (PMID 32201902, 2020). "Six studies included in this review reported changes in glucose profiles (either fasting blood glucose (FBG), insulin level, HOMA-IR, or quantitative insulin sensitivity check index (QUICKI)), and these studies involved obese subjects with a risk of CVD or type 2 diabetes and healthy obese subjects." (PMID 33266002, 2020). "MECR activity remains unknown in the mechanism of insulin resistance in the pathogenesis of type 2 diabetes." (PMID 32440681, 2020). "Considering variables prior to first examination in our cohort, hospitalized patients were older, had more massive obesity, type 2 diabetes with a longer duration and more macro- and microvascular complications together with comorbidities and treatment with insulin." (PMID 33233575, 2020). "A randomized controlled cross-over study of post-meal walking or one prandial insulin was done in type 2 diabetic patients who were being treated with basal insulin between May 2017 and March 2018." (PMID 32236116, 2020). "Finally, there has been a growing interest in non-insulin drugs, previously used to treat type 2 diabetes (T2D), regarding their potential protective effects on beta-cell function in autoimmune diabetes." (PMID 32872668, 2020). "Two studied variants (rs738409C>G in PNPLA3 and rs58542926 near TM6SF2) are positively associated with type 2 diabetes through large GWAS yet we found them not to be associated with fasting insulin or glucose." (PMID 32720691, 2020). "In summary, elevated WBC levels may be associated with alterations of glucose-related markers such as insulin, HOMA-IR, and adiponectin; thus, individuals with high WBC levels can be considered to be at high risk for type 2 diabetes." (PMID 32346379, 2020).
type 2 diabetes (continued). "Indeed, O-GlcNAcylation is associated with an increasing number of pathological states, such as type II diabetes mellitus, diabetic complications, insulin resistance, cancer, and neurodegeneration." (PMID 33330510, 2020). "One key driver of both type-2 diabetes and cancer is insulin." (PMID 32153503, 2020). "Also, OT treatment is associated with significant improvement in blood pressure, TC, LDL, the incidence of type II diabetes and the insulin sensitivity." (PMID 32948162, 2020). "Control of insulin sensitivity through neuromodulation, although generally relevant to type 2 diabetes, could be further extended for use in people with type 1 diabetes." (PMID 32467827, 2020). "Subpopulations of insulin granules carry different synaptotagmin isoforms and have different physical and fusion properties that correlate with those observed after type-1 and type-2 diabetes model treatments." (PMID 33164744, 2020). "Another MR study found insulin sensitivity polygenic score formed from a subset of type 2 diabetes associated SNPs, but not the overall type 2 diabetes polygenic score, was causally associated with Alzheimer’s disease." (PMID 33202379, 2020). "In conclusion, in this population based-cohort study, elevated C-peptide level is associated with an increased risk of type 2 diabetes independent of glucose, insulin levels, and other clinical factors in the general population." (PMID 32957570, 2020). "It is classified into type I diabetes mellitus (T1DM), which is considered as an autoimmune disease caused by loss of pancreatic β-cells, and type II diabetes mellitus (T2DM), caused by insulin resistance, although it eventually leads to impairment in insulin production and β-cell death." (PMID 33276470, 2020). "In our case series, all patients had type-2 diabetes established on insulin treatment." (PMID 33409023, 2020). "Medication had a significant impact on the incidence of level 2 hypoglycaemia, ranging from 1.5% in people with type 2 diabetes on metformin alone to 33% in people treated with a combination of rapid-acting insulin analogue, long-acting insulin analogue and i.v.-administered insulin." (PMID 32300821, 2020). "We then evaluated the association between age at PHV and the risk of a diagnosis of type 2 diabetes requiring insulin treatment (n = 787), i.e. type 2 diabetes with a worse global risk profile than type 2 diabetes without insulin treatment." (PMID 32201902, 2020). "Troglitazone and rosiglitazone belong to thiazolidinediones, which are syntheticPPAR-gamma agonists and act as insulin sensitizers to treat type 2 diabetes.However, PPAR-gamma has been considered to be a regulator of inflammation andischemic responses in recent years." (PMID 32696819, 2020). "In addition, a former study observed a similar improved insulin sensitivity in type 2 diabetics, when comparing the effect of diets high in animal-based protein to diets high in plant-based protein." (PMID 32443678, 2020). "Aging is characterized by different changes at the physiological and molecular level over time, such as the development of a resistance to the action of insulin, changes in body composition, and alterations in the lipid profile, all leading to the development of type 2 diabetes." (PMID 31974316, 2020). "Those with type 2 diabetes, especially with a higher body mass index, may also need higher doses of insulin detemir compared to insulin glargine or NPH insulin." (PMID 32396624, 2020). "In multivariable-adjusted Cox regression models, we observed a significant positive association of C-peptide with the risk of type 2 diabetes independent of glucose and insulin levels (hazard ratio (HR): 2.35; 95% confidence interval (CI): 1.49–3.70)." (PMID 32957570, 2020). "There is an additional hypothesis that magnesium deficiency has deleterious effects on glucose metabolism due to an impairment both in insulin secretion and its action, contributing to the development of type 2 diabetes (T2D)." (PMID 32085495, 2020).